TUBA1C (tubulin alpha 1c)
Diseases named in the same sentence as TUBA1C in open-access papers (continued):
Sharing a sentence is not in itself a finding about the gene and the disease.
tumor (continued). "By using the GEPIA database, we found that TUBA1C expression was significantly related to the following parameters: different disease states (tumor or normal) (P < 0.05), pathological stage (P = 1.82e−04), overall survival (P = 3.8e−0.5), and disease-free survival (P = 0.047)." (PMID 33653340, 2021). "TUBA1C may influence the tumor development process by regulating the tumor-infiltrating cells in the TME." (PMID 34721547, 2021). "Additionally, we evaluated the correlation between TUBA1C expression and tumor stage and found that the expression of TUBA1C was increased in stage III than stage II of LGG (p < 0.0001)." (PMID 34721547, 2021). "A boxplot was plotted using the data of expression of TUBA1C in normal and tumor tissues." (PMID 33653340, 2021). "Furthermore, functional assays including cell viability, apoptosis, cell cycle, transwell assay, wound healing assay, and a xenograft tumor model were performed to determine the oncogenic role of TUBA1C in PDAC, respectively." (PMID 32117719, 2020). "Collectively, our findings showed that the knockdown of TUBA1C suppresses tumor growth in vivo." (PMID 32117719, 2020). "Meanwhile, previous studies demonstrated TUBA1C upregulation could significantly impact tumor growth and progression." (PMID 32117719, 2020). "Besides, we noticed that TUBA1C was independent from gender, age, tumor size and differentiation, while it is significantly associated with membrane status." (PMID 29221200, 2017). "Additionally, collagen proteins (COL1A1, COL1A2, COL3A1, COL11A1) were linked to tumor progression and metastasis, while chaperonin-containing TCP1 (CCT) complex proteins and microtubule-associated proteins (TUBA1C, TUBB) were implicated in cytoskeletal organization and chemotherapy resistance." (PMID 40867231, 2025). "Furthermore, TUBA1C was found to be a key mediator in the cell cycle-signaling pathways, which show aberrant expression in multifarious malignant tumors; tumor multiplication, migration, and invasion; and as a novel target for tumor-targeted therapy." (PMID 36941595, 2023). "Therefore, although the role of TUBA1C may be heterogeneous in different tumours, TUBA1C mRNA expression can be used to predict the prognosis of some tumours." (PMID 36466547, 2022). "Therefore, we speculate that TUBA1C can serve as a new site for genetic testing in tumour treatment, thereby improving the prognosis." (PMID 36466547, 2022). "However, the GBM tumor tissues had strong TUBA1C IHC staining." (PMID 34721547, 2021). "TUBA1C may influence tumor development by regulating the tumor-infiltrating cells in the TME." (PMID 34721547, 2021). "Furthermore, we elucidated the potential relationship between TUBA1C and tumor-immune interaction." (PMID 33653340, 2021). "Furthermore, TUBA1C downregulation also inhibited tumor growth in vivo." (PMID 32117719, 2020). "Finally, the xenograft tumor model showed that downregulation of TUBA1C could promote cell apoptosis and inhibit tumor growth in vivo." (PMID 32117719, 2020). "Consistent with our initial observations, the results showed that TUBA1C expression levels were significantly correlated with TNM stage, tumor grades, and tumor stage." (PMID 39301023, 2024). "This pattern of heightened expression was also observed in tumor cells and TECs at the single-cell level following an ICB response, underscoring the pivotal role of TUBA1C in the TME post-therapy." (PMID 39301023, 2024). "Analysis of the tumor and TME signature scores in TCGA-KIRC cohort showed that, in line with that observed in the Braun ICB cohort, the group with elevated TUBA1C expression exhibited higher scores relating to carcinogenic pathways and TME activity." (PMID 39301023, 2024). "In our study, TUBA1C was significantly upregulated in BLCA, and its potential role in BLCA was revealed by silencing TUBA1C, which significantly suppressed BLCA cell migration and invasion, confirming its role in tumor progression." (PMID 37528357, 2023).
tumor (continued). "Overall, an inverse correlation was noted between tumor purity and the expression levels of IGF2BP3, EMP3, TUBA1C, AK2 and IGFBP2 (average PCC = −0.48)." (PMID 38171932, 2023). "Therefore, we further explored whether TUBA1C is related to tumor immunity in BLCA." (PMID 37528357, 2023). "TUBA1C, which is positively correlated with GPX8, has been reported to be a prognostic marker in LGG and correlated with immune cell infiltration in the tumor microenvironment." (PMID 36052280, 2022). "In order to determine the difference between the expression of TUBA1C in tumor tissues and normal tissues, we used TIMER algorithm to analyze the mRNA expression of TUBA1C in different types of tumors that were obtained from TCGA database." (PMID 33653340, 2021). "We further verified the high TUBA1C expression in LGG tumor tissues in the GEPIA, the result indeed showed that TUBA1C was over-expressed in LGG than normal tissues, which was consistent with our findings." (PMID 34721547, 2021). "As result, the α-tubulin isoforms TUBA1B, TUBBA1A and TUBA1C had the highest mRNA expression levels, while TUBA4B and TUBA8 had the lowest expression level among the tubulin isoforms in all the tumor samples." (PMID 30126203, 2018). "We then compared the protein abundance in normal-tumor-PVTT pairs, and the results showed that PVTT had a significantly higher protein abundance of TUBA1C than the primary tumor tissue." (PMID 29221200, 2017). "Additionally, hypoxic conditions prevalent in substantial tumor masses promote the progression of ccRCC, as supported by data from the Braun ICB and TCGA-KIRC cohorts, thus confirming the multifaceted role of TUBA1C in this malignancy." (PMID 39301023, 2024). "Overall, TUBA1C exhibits a common function across various cancer types, regulating the PI3K/AKT and cell cycle-related pathways and reshaping the TME, thereby influencing tumor progression and, consequently, leading to poor clinical outcomes." (PMID 39301023, 2024). "There is increasing evidence that TUBA1C regulates cell cycle progression in various cancer types, and TCGA-based KEGG enrichment analysis revealed that TUBA1C may promote tumor progression in HCC and LUAD through cell cycle signaling pathways." (PMID 37528357, 2023). "TUBA1C has also been shown to promote aerobic glycolysis by upregulating YAP expression to promote aerobic glycolysis and enhance lactate metabolism, glucose consumption, and cell growth, migration, and invasion, thereby promoting tumor progression in BRCA." (PMID 37528357, 2023). "Intriguingly, in PAAD (p = 0.022), TUBA1C expression was higher in stage II tumours than in stage I tumours, but no dramatic difference existed in stage III or IV tumours." (PMID 35513790, 2022). "In addition, the TUBA1C expression level was higher in HNSC-HPV+ tumours than in HNSC-HPV- tumours, and it was higher in SKCM tumours than in SKCM metastatic tumours." (PMID 35513790, 2022). "In the current study, we performed a systematic pancancer analysis of TUBA1C through databases such as Oncomine, CCLE, HPA, and TGCA to analyse its effects on cancer prognosis, clinicopathology, the immune response, and the tumour microenvironment and validated the findings by immunohistochemistry." (PMID 35513790, 2022). "TUBA1C, TUBA1B and the β-tubulin isoform TUBB were found as isoforms with the highest expression levels compared to other isoforms in BC cell lines, and TUBA1C and TUBB were overexpressed in BC tumours compared to the normal breast tissues." (PMID 35167614, 2022). "Previous studies have shown that TUBA1C can predict poor outcome in PDAC by modulating cell cycle signalling pathways to induce apoptosis, in LUAD and LGG by affecting TIICs in the tumour microenvironment, and in HCC by cell cycle signalling pathways." (PMID 35513790, 2022).
tumor (continued). "The results illustrated that the TUBA1C IHC staining was weak in the normal cerebral cortex, whereas LGG tumor tissues had not detected the TUBA1C IHC staining or had high TUBA1C IHC staining." (PMID 34721547, 2021). "After reviewing the literature, we found that four upregulated genes comprising of TUBA1C, ABCE1, UBE2N, and NIFK had been reported to function in tumor growth, proliferation, migration, metastasis, and prognosis." (PMID 31867042, 2019). "A total of 12 upregulated and one downregulated genes were found to overlap with prognostic and fitness genes, in which four upregulated genes (TUBA1C, ABCE1, UBE2N, and NIFK) had been reported to play roles in tumor growth, cell cycle, migration, metastasis, and prognosis." (PMID 31867042, 2019). "Analyzing expression profile of BC tumors and tumor-adjacent normal breast tissues showed upregulation of TUBA1A, TUBA1C, TUBB and TUBB3 and downregulation of TUBB2A, TUBB2B, TUBB6, TUBB7P pseudogene, and TUBGCP2 in the tumor tissues compared to the normal breast tissues." (PMID 30126203, 2018). "This strongly supports that TUBA1C recruits MDSCs and Tregs via the PI3K/AKT pathway, inducing an immunosuppressive phenotype in macrophages and dysfunction in CD8+ T cells, thereby reshaping the immunosuppressive tumor microenvironment and mediating ICB resistance in ccRCC." (PMID 39301023, 2024). "Multiple public databases were used to analyze the differential expression of TUBA1C and its prognostic role in BLCA, identify likely oncogenic pathways in BLCA based on GO and KEGG analysis, and discuss the correlations of TUBA1C with tumor immunity and drug response." (PMID 37528357, 2023). "Furthermore, the metastatic ability is increased along with TUBA1C abundance, according to protein abundance evaluation of normal-tumor-portal vein tumor thrombus pairs, and mRNA comparison between metastasis-averse HCC and metastasis-incline HCC." (PMID 29221200, 2017). "However, no studies have yet explored whether TUBA1C overexpression affects the tumor immune microenvironment of LGG." (PMID 34721547, 2021).
cancer (24 papers, 2016 to 2025). A tumor composed of atypical neoplastic, often pleomorphic cells that invade other tissues. "TUBA1C, which encodes a tubulin alpha chain essential for microtubule dynamics, is overexpressed in colorectal and other cancers." (PMID 41464182, 2025). "We next explored the association between TUBA1C expression and immune regulation and drug sensitivity in ccRCC given its putative importance in personalized cancer therapy research." (PMID 39301023, 2024). "This proteomic validation was used to select cancer-associated proteins and identified as the TUBA1C-test proteins, which directly bind to EGFR-AS1 in independent RNA pulldown assays." (PMID 36941595, 2023). "This study aims at assessing the role of TUBA1C in pan-cancer at multiple levels, including mutations, gene expression, methylation, m6A methylation, and immune cell infiltration levels." (PMID 36466547, 2022). "The cBioPortal database was used to evaluate the mutation frequency of TUBA1C and its specific mutation sites in 32 cancer types." (PMID 36466547, 2022). "Subsequently, we explored the association between TUBA1C expression and the prognosis of patients across cancers." (PMID 35513790, 2022). "The mutation frequency of TUBA1C in TCGA cohort (10,105 samples spanning 32 cancer types) was examined using the cBioPortal database." (PMID 36466547, 2022). "Previous studies have also reported that TUBA1C is associated with cell proliferation, and it also regulates cell cycle in many types of cancers." (PMID 33653340, 2021). "TUBA1C is a microtubule component implicated in multiple cancers, however, the clinical significance and biological functions of TUBA1C in the progression of PDAC remain unexplored." (PMID 32117719, 2020). "Some researches indicated that TUBA1C was implicated in cell proliferation and cell cycle in numerous cancers." (PMID 32117719, 2020). "Therefore, reduced expression of TUBA1C mRNA is a protective factor for the prognosis of most cancer types but a risk factor for the prognosis of READ." (PMID 36466547, 2022). "To date, studies have mainly focused on the impact of TUBA1C expression on the prognosis of different cancer types; however, the relationship between TUBA1C and mutations, immune-related genes, immune microenvironment, or drug sensitivity has not been examined." (PMID 36466547, 2022). "Although the underlying mechanisms remain unclear, the role of TUBA1C in cancer is attracting increasing attention." (PMID 36466547, 2022). "Cell cycle regulation is one of the important pathways associated with TUBA1C in pan-cancer." (PMID 36466547, 2022). "The TUBA1A gene encodes α-tubulin, which forms a dimer with β-tubulin to generate tubulin α1c (TUBA1C), a protein known to upregulate in various cancers and strongly correlate with poor survival." (PMID 40974979, 2025). "Further investigation showed that TUBA1C is not only highly expressed in KIRC but also in a broad spectrum of cancers, suggesting that it has a wide-ranging oncogenic role." (PMID 39301023, 2024). "These consistent outcomes across various cancer types highlighted the correlation between TUBA1C and CD274, positioning TUBA1C as a potential biomarker for targeted therapy." (PMID 39301023, 2024). "While methylation discrepancies in several regions of TUBA1C were primarily associatedwith ccRCC, these variations influenced the expression level of TUBA1C in various cancer types." (PMID 39301023, 2024). "This provided strong evidence supporting a crucial role for TUBA1C as an oncogene across several types of cancer." (PMID 39301023, 2024). "We identified a significant positive correlation between TUBA1C and CD274 at both the pan-cancer and pan-tissue levels, suggesting that TUBA1C has a strong and universal connection with CD274 under both physiological and pathological conditions." (PMID 39301023, 2024).
cancer (continued). "Elevated expression of the oncogene TUBA1C has been correlated with poor prognosis in various cancers, however, its role in ccRCC is unclear, especially concerning ICB resistance." (PMID 39301023, 2024). "Multiple studies have revealed the oncogenic role of tubulin alpha-1C chain (TUBA1C) in various cancer types." (PMID 39301023, 2024). "The results of the pan-cancer and pan-tissue analysis underscored the critical role of TUBA1C in cancer biology and its potential as a prognostic marker in ccRCC." (PMID 39301023, 2024). "α1C-tubulin (TUBA1C) is a member of the α-tubulin family and has served as a potential biomarker in a variety of cancers in many studies." (PMID 38032902, 2023). "Recently, substantial evidence has indicated that α1C-tubulin (TUBA1C), which is a component of microtubules, is closely related to the occurrence and development of a variety of cancers." (PMID 38032902, 2023). "In this study, TUBAC was found to be overexpressed in most cancer types, which was verified via proteomic analysis (high expression of TUBA1C protein in COAD, LUAD, BRCA, and PRAD)." (PMID 36466547, 2022). "TUBA1C was coexpressed with MHC genes in several cancer types, particularly BLCA, ESCA, LGG, LICH and THCA." (PMID 35513790, 2022). "We found that TUBA1C was correlated with immune checkpoints in all cancers except UVM, KIRC and ACC." (PMID 35513790, 2022). "In particular, it was positively correlated with almost all immunosuppressive, chemotactic and chemotactic receptor genes in LGG, LIHC, and THCA, suggesting that TUBA1C influences the prognosis of these three cancer types through immune-related genes." (PMID 36466547, 2022). "We first examined the association between TUBA1C expression level and TMB and MSI, two indicators that predict the sensitivity of cancer patients to ICIs." (PMID 35513790, 2022). "In this study, a comprehensive analysis was performed to assess the role of TUBA1C as an immune checkpoint in the prognosis and treatment of cancer." (PMID 36466547, 2022). "Because the proportion of normal tissues in TCGA database was inadequate, normal tissue samples from GTEx were compared with cancer tissue samples from TCGA to analyse differential TUBA1C expression." (PMID 36466547, 2022). "The results suggest that TUBA1C is a promising prognostic biomarker for immunotherapy of pan-cancer." (PMID 36466547, 2022). "We can assume that in cancers where TUBA1C expression is positively correlated with TMB or MSI, a high TUBA1C level predicts a good outcome and prognosis for immunotherapy." (PMID 35513790, 2022). "The results showed that TUBA1C activated apoptosis and promoted the cell cycle in pan-cancer, which is consistent with the findings of previous studies." (PMID 36466547, 2022). "TUBA1C was coexpressed with most chemokines except CCL27, and coexpression of TUBA1C with chemokines and chemokine receptors was observed in most cancers except UVM (C, D)." (PMID 35513790, 2022). "In this study, the relationship between TUBA1C and the immune microenvironment of pan-cancer was examined by analysing the correlation between TUBA1C and immune cell infiltration." (PMID 36466547, 2022).